ZSCAN9 (zinc finger and SCAN domain containing 9)
Description:
May be involved in transcriptional regulation.
Synonyms: ZNF193; PRD51
Tractability: PROTAC: UniProt records ubiquitination sites on it; ubiquitination databases record sites on it.
Gene: Protein-coding gene on chromosome 6 (28,224,886 to 28,233,487, forward strand). Ensembl gene ENSG00000137185.
Subcellular location: Nucleus
Subcellular location (Human Protein Atlas): Nucleoplasm; Cytosol
Gene Ontology:
Molecular function: protein binding; sequence-specific double-stranded DNA binding; DNA-binding transcription factor activity, RNA polymerase II-specific; RNA polymerase II cis-regulatory region sequence-specific DNA binding
Biological process: regulation of transcription by RNA polymerase II
Cellular component: nucleus
Genetic constraint (gnomAD): Loss-of-function variants: 19 observed, 24.53 expected, observed/expected ratio (o/e) 0.77, 90% interval 0.54 to 1.14. The upper end of that interval is the gene's LOEUF score, 1.14, which puts it in group 4 of 6, group 1 being the genes least tolerant of losing a copy. Missense variants: 467 observed, 496.26 expected, observed/expected ratio (o/e) 0.94, 90% interval 0.87 to 1.02. Synonymous variants: 155 observed, 174.94 expected, observed/expected ratio (o/e) 0.89, 90% interval 0.78 to 1.01.
Homologues: Orthologues: chimpanzee ZSCAN9 (99% identical), macaque ZSCAN9 (94% identical), pig ZSCAN9 (84% identical), guinea pig ZSCAN9 (79% identical). Paralogues in human: ZSCAN23 (51% identical), ZKSCAN8 (48% identical), ZSCAN12 (47% identical), ZKSCAN3 (46% identical), ZKSCAN4 (46% identical), ZNF397 (45% identical), ZSCAN30 (44% identical), ZNF24 (44% identical), ZSCAN31 (44% identical), ZKSCAN1 (43% identical), ZSCAN16 (42% identical), ZNF165 (42% identical), and 18 more.
Diseases named in the same sentence as ZSCAN9 in open-access papers:
ZSCAN9 is named in the same sentence as 5 diseases in open-access papers, as found by Europe PMC text mining. Sharing a sentence is not in itself a finding about the gene and the disease. The quoted sentences say what the papers report.
cancer (1 paper, 2019). A tumor composed of atypical neoplastic, often pleomorphic cells that invade other tissues. "In the literature, genetic variants around ERAP2 have been associated with autoimmunity related disorders, whereas the ZSCAN9 gene is surrounded by the risk variants for neuropsychiatric diseases and cancer." (PMID 31244887, 2019).
ZSCAN9 also shares sentences with these, for which no sentence is quoted: epilepsy (1 paper); hemochromatosis (1); psychotic disorder (1); schizophrenia (1).